ZNF782 (zinc finger protein 782)
Description:
May be involved in transcriptional regulation.
Synonyms: FLJ16636
Tractability: PROTAC: ubiquitination databases record sites on it.
Gene: Protein-coding gene on chromosome 9 (96,815,490 to 96,875,623, reverse strand). Ensembl gene ENSG00000196597.
Subcellular location: Nucleus
Subcellular location (Human Protein Atlas): Mitochondria; Nucleoplasm
Pathways (Reactome):
Gene expression (Transcription): Generic Transcription Pathway
Gene Ontology:
Molecular function: transcription cis-regulatory region binding
Biological process: negative regulation of transcription by RNA polymerase II; regulation of DNA-templated transcription
Cellular component: nucleus
Genetic constraint (gnomAD): Loss-of-function variants: 7 observed, 9.23 expected, observed/expected ratio (o/e) 0.76, 90% interval 0.43 to 1.42. That is too few expected variants to judge how well the gene tolerates losing a copy. Missense variants: 751 observed, 848.43 expected, observed/expected ratio (o/e) 0.89, 90% interval 0.83 to 0.94. Synonymous variants: 279 observed, 291.15 expected, observed/expected ratio (o/e) 0.96, 90% interval 0.87 to 1.06.
Homologues: Orthologues: chimpanzee ZNF782 (99% identical), macaque ZNF782 (94% identical), dog ZNF782 (78% identical), pig ZNF782 (77% identical), rabbit ZNF782 (76% identical). Paralogues in human: ZNF300 (43% identical), ZNF658 (42% identical), ZNF182 (42% identical), ZNF33B (41% identical), ZNF630 (40% identical), ZNF717 (40% identical), ZNF484 (40% identical), ZNF334 (38% identical), ZNF41 (38% identical), ZNF33A (38% identical), ZNF605 (38% identical), ZNF175 (38% identical), and 164 more.